CDK2 (cyclin dependent kinase 2)
Diseases named in the same sentence as CDK2 in open-access papers (continued):
Sharing a sentence is not in itself a finding about the gene and the disease.
metastatic carcinoma (3 papers, 2016 to 2022). A carcinoma which has spread from the original site of growth to another anatomic site. "In metastatic carcinoma CaOV-3, both ObR antagonists had an inhibitory effect on the cdk2/cyclin D1 complex, while in serous carcinoma, OVCAR-3, they only had an effect on cdk2 and cdk4 protein expression." (PMID 27480179, 2016).
prostate tumor (3 papers, 2014 to 2025). "Importantly, MYBL2 was among these master regulators, and a recent report demonstrates MYBL2-expressing, stem-like prostate tumors may be susceptible to CDK2 inhibition." (PMID 40624104, 2025). "Surprisingly, gene expression of CDK7 negatively correlated to CDK2, SKP2, and CCNA2 in both GSE6919 and Singh prostate tumor datasets." (PMID 25271736, 2014). "Indeed, analysis of oncomine data indicated that gene expression level of SKP2, CDK2, and CCNA2 correlated positively well in both GSE6919 and Singh prostate tumor datasets." (PMID 25271736, 2014).
synovial sarcoma (3 papers, 2017 to 2026). "In contrast, synovial sarcomas (SS) frequently exhibit overexpression of CDK2, CDK4, and MDM2, loss of CDKN2A, and mutations in genes such as CDK 4/6." (PMID 38275873, 2024). "Consistent with the inhibition of G1-to-S phase progression, we found decreased cyclin D1 expression and decreased phosphorylation of CDK4 and CDK2 in synovial sarcoma cells in response to SAHA, LBH-589, and PXD101." (PMID 29100385, 2017). "In contrast, myxoid liposarcoma and synovial sarcomas exhibited marked sensitivity to SNS-032, a CDK2/7/9 inhibitor identified by our screen." (PMID 42165630, 2026).
adenomyosis (2 papers, 2019 to 2020). The growth of endometrial tissue inside the muscular wall of the uterine corpus. "We found that mifepristone causes cell cycle arrest through inhibiting CDK1 and CDK2 expressions and induces cell apoptosis via the mitochondria‐dependent signalling pathway in endometrial epithelial cells and stromal cells of adenomyosis." (PMID 31814282, 2020).
carcinoids (2 papers, 2015 to 2016). "ASCL1 (p = 0.0016), BCL2 (p < 0.0001), CASP8 (p = 0.0030), CCNE1 (p = 0.0135), CDK1 (p = 0.0146), CDK2 (p = 0.0114), CDKN1A (p = 0.0107) and CDKN2A (p = 0.0002) showed lower expression in carcinoids compared to carcinomas." (PMID 26008974, 2015). "In addition, IFN-α inhibited cyclin dependent kinases (CDK), CDK2-, CDK3-, CDK4-, and cyclin E- but not cyclin A-associated kinase activities and induced cell cycle arrest in carcinoid tumor." (PMID 26993600, 2016).
chondrosarcoma (2 papers, 2015 to 2025). A malignant cartilaginous matrix-producing mesenchymal neoplasm arising from the bone and soft tissue. "FGF2 treatment caused an elevation in the expression of p21, leading to the formation of complexes involving cyclin D2-Cdk4-p21, cyclin D2-Cdk2-p21, and cyclin E-Cdk2-p21, and reducing the activity of cyclin-dependent kinase 2 (Cdk2) and cyclin E-dependent kinases in rat chondrosarcoma cells." (PMID 40256430, 2025).
colon adenocarcinoma (2 papers, 2016 to 2022). "ZNF692 promotes cell proliferation, migration, and invasion in colon adenocarcinoma (COAD) by downregulating p27kip1 or upregulating cyclin D1, cyclin-dependent kinase 2 (CDK2), matrix metalloproteinase-9 (MMP-9), and PI3K/Akt signaling." (PMID 36358661, 2022). "It has been reported that the HDACi NaB induces G1-arrest in colon adenocarcinoma cells by stimulating cyclin D and p21WAF1/CIP1 and inhibiting CDK2 expression." (PMID 27716272, 2016).
crescentic glomerulonephritis (2 papers, 2016). A histopathologic term for a pattern of diseases characterized by extensive crescent formation in the glomeruli; patients present clinically with rapid deterioration of renal function, and possible progression to end-stage renal failure within weeks or months. "In human crescentic glomerulonephritis, the activation of cyclin A may be crucial for cell proliferation, while in focal segmental glomerulosclerosis patients, cyclins E, A, and B1 and CDK2 are involved in cell proliferation." (PMID 26359229, 2016).
diabetic nephropathy (2 papers, 2024 to 2025). "Additionally, a study in mice showed that increased expression of CDK2 protects podocytes (i.e., a layer of cells around the glomerulus in which filtration of blood takes place) from apoptosis, while reduced expression of CDK2 leads to increased susceptibility to diabetic nephropathy." (PMID 39202351, 2024).
ductal breast carcinoma (2 papers, 2024 to 2025). "Ectopic CDK2 expression has been linked to ductal breast carcinoma pathogenesis, with high nuclear CDK2 levels correlating with aggressive phenotypes, particularly high tumor grade, and lymph vascular invasion." (PMID 40017494, 2025).
epilepsy (2 papers, 2021 to 2025). A brain disorder characterized by episodes of abnormally increased neuronal discharge resulting in transient episodes of sensory or motor neurological dysfunction, or psychic dysfunction. "In short, CDK2 can be activated by pathways triggered by Aβ in AD, in turn, leading to neuronal excitability and potentially epilepsy." (PMID 41386826, 2025). "Thus, it suggests a correlation between epilepsy, CDK2, and Aβ." (PMID 41386826, 2025). "While its direct relevance to antiepileptic effects via CDK2 modulation requires further experimental validation, the implication of CDK dysregulation in neuronal network hyperexcitability and epilepsy warrants investigation into this potential target." (PMID 41386826, 2025). "CDK2 and PARP genes are involved in cell cycle control and apoptosis; it is well known that epilepsy leads to the apoptosis of several neurons." (PMID 33445780, 2021).
fibrosarcoma (2 papers, 2018 to 2025). A malignant mesenchymal fibroblastic neoplasm affecting the soft tissue and bone. "We used CRISPR-Cas9 technology to generate Cdk2-/- MCA205 fibrosarcomas cells that lacked Cdk2 expression." (PMID 40557162, 2025).
focal segmental glomerulosclerosis (2 papers, 2016 to 2017). A renal disorder characterized by sclerotic lesions in the glomeruli. "For example, in the cellular type of human FSGS (focal segmental glomerulosclerosis), studies have found absent p27, p57, and cyclin D1 expression and increased cyclin E, cyclin A, cyclin B1, CDK2, and p21." (PMID 28164134, 2017).
glomerular diseases (2 papers, 2016 to 2018). "Inhibiting CDK2 activity has also been considered a potential therapeutic target for glomerular diseases characterized by podocyte proliferation." (PMID 29950996, 2018). "Since mature podocytes are terminally differentiated and therefore have a limited capacity to proliferate, the role of CDK2 in healthy, nonproliferating podocytes and nonproliferative glomerular diseases, such as DN, remains unclear." (PMID 26876672, 2016). "However, in differentiated podocytes and nonproliferative glomerular diseases, such as DN, inhibition of CDK2 in podocytes may lead to or aggravate podocyte injury." (PMID 26876672, 2016).
hypothyroidism (2 papers, 2021 to 2024). Abnormally low levels of thyroid hormone. "The relative expression of three cell cycle promoters (CDK1, CDK2, and CDK4), and one cell cycle inhibitor (CDKN1A) was compared in each tissue to determine the effect of hypothyroidism on the developing fetus." (PMID 38902754, 2024).
injury (2 papers, 2024). Damage inflicted on the body as the direct or indirect result of an external force, with or without disruption of structural continuity. "In this study, we found that the HuR protein expression was inducible in the mouse model of APAP‐induced liver injury and found that HuR could protect against APAP‐induced liver injury by promoting the expression of NRF2, cyclin A1, cyclin B1, cyclin D1, CDK2, ATG3, ATG5 and ATG7." (PMID 39614424, 2024).
kidney injuries (2 papers, 2018 to 2019). "Similar to early inflammatory pathway-associated genes, SS-31 treatment could not modulate the upregulation of cyclin-dependent kinase 2 (CDK2), an enzyme involved in the G1-S transition phase of the cell cycle, induced during severe acute kidney injury after AA administration." (PMID 31780923, 2019).
latent infection (2 papers, 2008 to 2023). "In latent infection, CDK2 activity is needed to maintain cell cycle progression and to phosphorylate RB." (PMID 18605998, 2008). "The cell proliferation marker MKI67 as well as genes involved in G1-S and G2-M transition, such as CDK1, CDK2, CCNE2, PRIM2, AKT1, and FOXM1, were significantly downregulated in latent infection compared to actively infected cells." (PMID 38038477, 2023).
Lewis lung carcinoma (2 papers, 2013 to 2020). "Furthermore, the growth rate of Lewis lung carcinoma cells is reduced upon miR-223 overexpression by targeting cyclin-dependent kinase 2 (CDK2)." (PMID 32509795, 2020).
mesothelioma (2 papers, 2012 to 2022). A usually malignant and aggressive neoplasm of the mesothelium which is often associated with exposure to asbestos. "To further understand the role of SphK1 in mesothelioma cell proliferation, we next treated the cells with SphK inhibitor and determined the effect on phosphorylation of cyclin dependent kinase 2 (CDK2), which is essential for eukaryotic cell cycle G1/S phase transition." (PMID 23028939, 2012). "Furthermore, lower expression of CDK7, AKT1, PARP1 (p < 0.1), CCND2 (cyclin D2), CDK2, CDK4, BIRC5 (survivin), PCNA and CDH2 (N-cadherin) (p < 0.005) have been shown to result in longer median survival of patients with mesothelioma." (PMID 36304150, 2022).
neuroendocrine tumor (2 papers, 2010 to 2022). "Indeed, the inability of p27P69L to bind to Cdk2 associates with impaired growth suppression of GH3 neuroendocrine tumor cells in vitro." (PMID 20824794, 2010). "Consistently with these literature reports, we found that IGF2BP1 affects expression of EZH2 and its downstream effectors regulating cell proliferation, such as CDK2 and CCNE1 in neuroendocrine tumor cells, thereby driving G1/S transition." (PMID 35565249, 2022).
pulmonary fibrosis (2 papers, 2021 to 2022). Chronic progressive interstitial lung disorder characterized by the replacement of the lung tissue by connective tissue, leading to progressive dyspnea, respiratory failure, or right heart failure. "By analyzing the target interaction network VCAM1,RELA,CDK2,JUN,CDK1,HSP90AA1,NOS2, SOD1,CASP3,AHSA1, PTGER3 are at the core of the network, which can be regarded as the key targets of Astragalus polysaccharides in treating pulmonary fibrosis." (PMID 35370663, 2022).
retinal degeneration (2 papers, 2022 to 2023). Degeneration of the retina. "Interference of miR-155-5p expression in NaIO3-induced retinal degeneration cell model reduced cell apoptosis and intracellular ROS levels; moreover, miR-155-5p could target CDK2." (PMID 36824443, 2023). "A previous study demonstrated the expression of cell cycle proteins, such as cyclin dependent kinase 2 and cyclin dependent kinase 4, in rd1, but details of CDK1 expression during retinal degeneration have, to our knowledge, not been reported." (PMID 35883586, 2022).
rheumatoid arthritis (2 papers, 2023 to 2024). A chronic, systemic autoimmune disorder characterized by inflammation in the synovial membranes and articular surfaces. "MiR-124a significantly inhibits CDK2 expression in synovial cells of patients with rheumatoid arthritis (RA), thereby inhibiting cell proliferation and arresting the cell cycle in the G1 phase." (PMID 37240281, 2023).
serous carcinoma (2 papers, 2016 to 2024). "High cytoplasmic CDK2 expression showed a significant association with serous carcinoma (adjusted p value = 0.005)." (PMID 38612869, 2024).
squamous carcinoma (2 papers, 2012 to 2020). "It was shown that upon DNA damage in squamous cell carcinoma cells, ATM kinase is a master switch for the DNp63α phosphorylation at S385 and it’s degradation upon subsequent phosphorylation by CDK2 and p70s6K kinases." (PMID 33375680, 2020). "However, in squamous carcinoma A431 cells, which express high levels of endogenous EGFR, EGF at pM range stimulates cell growth, while at nM range inhibits proliferation, arrests cell cycle, alters cdk2 activity by induction of p21, and even induces cell apoptosis." (PMID 22927910, 2012).
stomach adenocarcinoma (2 papers, 2021 to 2023). "It is known that cyclin A and cdk2 have a complex role in cancer and are frequently mutated and overexpressed in several tumor types, including stomach adenocarcinoma." (PMID 38203419, 2023). "The analysis includes comparison of the three targets (CDK2, MMP1, and HSP90) between 408 stomach adenocarcinoma (STAD) samples and non-tumor stomach tissues." (PMID 33921173, 2021).
T-cell acute lymphoblastic leukemia (2 papers, 2021 to 2022). Acute lymphoblastic leukemia of T-cell origin. "In patients with T-cell acute lymphoblastic leukemia (T-ALL), HIF-1α is overexpressed, and HIF-1α can promote the activation of Notch1 signaling, increase the expression of cyclin D1, CDK2, p21, MMP2, and MMP9 proteins, thereby leading to cell proliferation, invasion, and resistance." (PMID 35684364, 2022).
uveal melanoma (2 papers, 2024). A melanoma derived from melanocytes of the uveal tract. "Inhibiting them with a specific Gq/11 inhibitor caused CDK1 and CDK2 deactivation, highlighting their role in cell progression in uveal melanoma." (PMID 39598629, 2024).
acute lymphoblastic leukemia (1 paper, 2014). Leukemia with an acute onset, characterized by the presence of lymphoblasts in the bone marrow and the peripheral blood. "The exponentially growing acute lymphoblastic leukemia cell line, MOLT-4 cells, was cultured with or without a CDK2 inhibitor, GW8510 or Chk2 inhibitor II, for 6 h, and phosphorylation of pRB was evaluated by site-specific phospho-serine/threonine antibodies." (PMID 24466208, 2014).
acute megakaryocytic leukaemia (1 paper, 2023). "BIKE also negatively regulates polyploidy and megakaryocyte differentiation in acute megakaryocytic leukaemia by interacting with cyclin-dependent kinase 2 (CDK2) and promoting mitosis." (PMID 37955299, 2023).
acute pancreatitis (1 paper, 2022). An acute inflammatory process that leads to necrosis of the pancreatic parenchyma. "qPCR data also confirmed the upregulated levels of IL‐23a, IL‐17a, and IL‐17f and the downregulated levels of ATM, Cdk2, and Chk2 in the pancreatic tissues of mice with acute pancreatitis." (PMID 35634959, 2022). "To further evaluate the role of cell cycle‐related molecules during acute pancreatitis, we knockdown Cdk2 in the RAW264.7 cells, which was confirmed by qPCR and Western blot." (PMID 35634959, 2022). "RNA‐seq data discovered that compared to untreated mice, IL‐23a, IL‐17a, and IL‐17f were remarkably increased while cell cycle‐related molecules, including ATM, Cdk2, and Chk2, were decreased in the mice with acute pancreatitis." (PMID 35634959, 2022). "Cdk2 negatively regulates IL‐23 expression by inhibiting DCAF2 in acute pancreatitis, indicating that Cdk2 might serve as a promising therapeutic target for acute pancreatitis." (PMID 35634959, 2022). "Cdk2 and Chk2 expressions were reduced in the PBMC of patients with acute pancreatitis in comparison with the ones from healthy donors." (PMID 35634959, 2022). "Our data elucidated the regulatory effect of Cdk2 and DCAF2 on IL‐23 expression in acute pancreatitis." (PMID 35634959, 2022). "Our study first discovered that the expression of IL‐23 was significantly increased by RNA‐seq in mice with severe acute pancreatitis, with a remarkable decrease in the expressions of cell cycle‐related molecules, including ATM, Cdk2, and Chk2." (PMID 35634959, 2022).
adrenal adenoma (1 paper, 2018). "We confirmed this finding in an independent dataset (GSE33371) and found significantly higher CDK1 and CDK2 mRNA expressions in ACC (n=33) compared to normal (n=10, p<0.01) and adrenal adenoma (n=22, p<0.01)." (PMID 30250647, 2018). "In GSE12368 dataset, CDK1 and CDK2 mRNA expressions were significantly higher in ACC (n=12) compared to normal (n=6, p=0.02) and adrenal adenoma (n=16, p<0.01)." (PMID 30250647, 2018).
amyotrophic lateral sclerosis (1 paper, 2018). Amyotrophic lateral sclerosis (ALS) is a neurodegenerative disease characterized by progressive muscular paralysis reflecting degeneration of motor neurons in the primary motor cortex, corticospinal tracts, brainstem and spinal cord. "Because kenpaullone was a candidate therapeutic for amyotrophic lateral sclerosis and cardiac parasympathetic dysfunction, our findings suggest that CDK2 might also contribute to the protective effects of kenpaullone against amyotrophic lateral sclerosis and cardiac parasympathetic dysfunction." (PMID 29514916, 2018).
autoimmune disease (1 paper, 2023). A disorder resulting from loss of function or tissue destruction of an organ or multiple organs, arising from humoral or cellular immune responses of the individual to their own tissue constituents. "Additionally, elevated CDK2 abundance was found in sera of patients with the autoimmune disease Pemphigus Vulgaris, with CDK2 inhibition limiting the development of pathologies in a mouse model system of this disease." (PMID 37283074, 2023).
autoimmune uveitis (1 paper, 2013). An autoimmune form of uveitis (disease). "In this study, our overall goal is to test targeting CdK2 as a novel strategy to modulate CD4+ T cell response and thus treat autoimmune uveitis." (PMID 24260551, 2013).
Cerebral ischemia (1 paper, 2023). Restriction of arterial blood supply to the brain associated with insufficient oxygenation to support the metabolic requirements of the tissue. "Among these proteins, activation of cell cycle protein-dependent kinases (CDKs) such as CDK2 may cause neuronal death after cerebral ischemia." (PMID 36959823, 2023).
cervical (1 paper, 2020). "circ_0084927 promoted cervical carcinogenesis by sequestering miR-1179, which directly targeted CDK2." (PMID 32699532, 2020).
cervical squamous cancer (1 paper, 2020). "By querying GEPIA expression data, we also found that CDK2 was significantly up-regulated in cervical squamous cancer (CESC) tissue samples." (PMID 32699532, 2020).
childhood cancer (1 paper, 2023). "CDK2 is associated with CCND1, which regulates cell proliferation, the cell cycle, and DNA damage repair in childhood cancer through the regulation of Rb." (PMID 37444539, 2023).
chronic kidney disease (1 paper, 2019). Impairment of the renal function secondary to chronic kidney damage persisting for three or more months. "This study shows that cell proliferation, differentiation, apoptosis, migration (SRC, HRAS, HSP90AA1, CDK2), and ameliorating chronic kidney disease (MAPK14, F2, LCK, MMP9) appear to play important roles in the therapeutic effect of SQW." (PMID 31275142, 2019).
Cirrhosis (1 paper, 2012). A chronic disorder of the liver in which liver tissue becomes scarred and is partially replaced by regenerative nodules and fibrotic tissue resulting in loss of liver function. "Overall, critical genes encoding for positive cell cycle progression factors (CCND1, CDK1, CDK2, E2F3, EIF4E, and MDM2) were found significantly up-regulated in HCV-cirrhosis with HCC." (PMID 22792259, 2012).
Co-infection (1 paper, 2010). "Co-infection of Sf9 cells with either recombinant baculovirus directing expression of wild type or P45L cdk2 and either an A- or E-type cyclin was performed and the kinase activity of the cell lysates assessed." (PMID 20399812, 2010).
endometrial tumors (1 paper, 2016). "Analysis of the Cancer Genome Atlas (TCGA) database of endometrial tumors identified an inverse correlation between PR and Myc mRNA levels, with a corresponding inverse correlation between PR and Myc downstream transcriptional targets SRD5A1, CDK2 and CCNB1." (PMID 26859414, 2016).